RNU6-18P (RNA, U6 small nuclear 18, pseudogene)
Synonyms: RNU6-18
Gene: Small nuclear RNA gene on chromosome 15 (32,284,152 to 32,284,258, forward strand). Ensembl gene ENSG00000207257.
Homologues: Orthologues: rat U6 (100% identical), dog U6 (96% identical), mouse Gm23947 (94% identical), guinea pig U6 (90% identical), pig U6 (87% identical). Paralogues in human: RNU6-17P (100% identical), RNU6-1 (99% identical), RNU6-12P (99% identical), RNU6-13P (99% identical), RNU6-2 (99% identical), RNU6-32P (99% identical), RNU6-3P (99% identical), RNU6-4P (99% identical), RNU6-5P (99% identical), RNU6-6P (99% identical), RNU6-9 (99% identical), RNU6-25P (98% identical), and 1289 more.